ZFP36L2 (ZFP36 like 2 zinc finger CCCH-type)
Description:
Zinc-finger RNA-binding protein that destabilizes several cytoplasmic AU-rich element (ARE)-containing mRNA transcripts by promoting their poly(A) tail removal or deadenylation, and hence provide a mechanism for attenuating protein synthesis. Acts as a 3'-untranslated region (UTR) ARE mRNA-binding adapter protein to communicate signaling events to the mRNA decay machinery. Functions by recruiting the CCR4-NOT deadenylase complex and probably other components of the cytoplasmic RNA decay machinery to the bound ARE-containing mRNAs, and hence promotes ARE-mediated mRNA deadenylation and decay processes. Binds to 3'-UTR ARE of numerous mRNAs. Positively regulates early adipogenesis by promoting ARE-mediated mRNA decay of immediate early genes (IEGs). Plays a role in mature peripheral neuron integrity by promoting ARE-containing mRNA decay of the transcriptional repressor REST mRNA. Plays a role in ovulation and oocyte meiotic maturation by promoting ARE-mediated mRNA decay of the luteinizing hormone receptor LHCGR mRNA. Acts as a negative regulator of erythroid cell differentiation: promotes glucocorticoid-induced self-renewal of erythroid cells by binding mRNAs that are induced or highly expressed during terminal erythroid differentiation and promotes their degradation, preventing erythroid cell differentiation. In association with ZFP36L1 maintains quiescence on developing B lymphocytes by promoting ARE-mediated decay of several mRNAs encoding cell cycle regulators that help B cells progress through the cell cycle, and hence ensuring accurate variable-diversity-joining (VDJ) recombination process and functional immune cell formation. Together with ZFP36L1 is also necessary for thymocyte development and prevention of T-cell acute lymphoblastic leukemia (T-ALL) transformation by promoting ARE-mediated mRNA decay of the oncogenic transcription factor NOTCH1 mRNA.
Synonyms: ERF-2; ERF2; RNF162C; TIS11D; BRF2; OOMD13; OZEMA13
Tractability: PROTAC: ubiquitination databases record sites on it.
Gene: Protein-coding gene on chromosome 2 (43,222,402 to 43,226,606, reverse strand). Ensembl gene ENSG00000152518.
Subcellular location: Nucleus; Cytoplasm
Pathways (Reactome):
Developmental Biology: M-decay: degradation of maternal mRNAs by maternally stored factors
Gene Ontology:
Molecular function: mRNA 3'-UTR AU-rich region binding; protein binding; RNA binding; mRNA regulatory element binding translation repressor activity; protein-RNA sequence-specific adaptor activity; metal ion binding; mRNA binding
Biological process: 3'-UTR-mediated mRNA destabilization; cellular response to epidermal growth factor stimulus; cellular response to fibroblast growth factor stimulus; cellular response to glucocorticoid stimulus; cellular response to granulocyte macrophage colony-stimulating factor stimulus; cellular response to transforming growth factor beta stimulus; cellular response to tumor necrosis factor; ERK1 and ERK2 cascade; mRNA catabolic process; regulation of mRNA stability; response to wounding; definitive hemopoiesis; hemopoiesis; negative regulation of fat cell differentiation; negative regulation of mitotic cell cycle phase transition; negative regulation of stem cell differentiation; nuclear-transcribed mRNA poly(A) tail shortening; positive regulation of nuclear-transcribed mRNA catabolic process, deadenylation-dependent decay; regulation of B cell differentiation; somatic stem cell division; somatic stem cell population maintenance; T cell differentiation in thymus; MAPK cascade; negative regulation of translation
Cellular component: cytoplasm; nucleus; cytosol
Genetic constraint (gnomAD): Loss-of-function variants: 16 observed, 16.03 expected, observed/expected ratio (o/e) 1, 90% interval 0.68 to 1.51. The synonymous counts are far from expectation, so gnomAD's model fits this gene poorly and the ratio says little. Missense variants: 989 observed, 621.66 expected, observed/expected ratio (o/e) 1.59, 90% interval 1.51 to 1.68. Synonymous variants: 600 observed, 326.44 expected, observed/expected ratio (o/e) 1.84, 90% interval 1.72 to 1.95.
Homologues: Orthologues: macaque ZFP36L2 (99% identical), chimpanzee ZFP36L2 (97% identical), pig ZFP36L2 (96% identical), dog ZFP36L2 (94% identical), rat Zfp36l2 (90% identical), mouse Zfp36l2 (88% identical), rabbit ZFP36L2 (84% identical), guinea pig ZFP36L2 (72% identical), tropical clawed frog zfp36l2 (54% identical), zebrafish zfp36l2 (41% identical), Caenorhabditis elegans ccch-1 (22% identical), Caenorhabditis elegans gla-3 (20% identical), and 17 more. Paralogues in human: ZFP36L1 (40% identical), ZFP36 (23% identical).
Diseases named in the same sentence as ZFP36L2 in open-access papers:
ZFP36L2 is named in the same sentence as 73 diseases in open-access papers, as found by Europe PMC text mining. Sharing a sentence is not in itself a finding about the gene and the disease. The quoted sentences say what the papers report.
colorectal cancer (7 papers, 2004 to 2022). A primary or metastatic malignant neoplasm that affects the colon or rectum. "Loss of function of ZFP36L2 was frequently observed in recurrent colorectal cancers." (PMID 35343095, 2022). "The result showed that ZFP36L2 was highly expressed in colorectal cancer, lower-grade gliomas, leukemia, hepatic cancer, ovarian cancer, pancreatic cancer and gastric cancer compared with normal tissues." (PMID 35910229, 2022). "ZFP36L2 is a putative transcription factor involved in cellular responses, which was shown to act as a tumor suppressor in colorectal cancer and acute myeloid leukemia." (PMID 32252688, 2020). "To confirm the effects of ZFP36L1 and ZFP36L2 on tumor cells, we used seven human colorectal cancer cell lines to screen expressions of ZFP36L1 and ZFP36L2 by using western blot analysis." (PMID 29426877, 2018). "A study showed that the recurrence-free survival of patients with loss of function of ZFP36L2 was significantly shorter than that of patients with no loss of ZFP36L2 function in colorectal cancer." (PMID 36644636, 2022). "In addition, we confirmed that ZFP36L2 protein fluctuated during the cell cycle, not only in HeLa cells but also in the near-diploid human colorectal cancer cell line HCT116, by greatly down-regulating its protein level at the post-mitotic stages." (PMID 29449217, 2018). "Furthermore, the recurrence‐free survival of colorectal cancer patients with loss of function of ZFP36L2 was significantly shorter relative to patients with no loss of ZFP36L2 function." (PMID 35343095, 2022). "With further detection of G1 phase-related molecule expressions, we found that forced expression of ZFP36L1 or ZFP36L2 markedly reduced cyclin D protein expression but did not change expressions of other molecules, including cyclin A, Cdk2, or Cdk4, in these three types of colorectal cancer cell." (PMID 29426877, 2018).
leukemia (7 papers, 2014 to 2024). A malignant (clonal) hematologic disorder, involving hematopoietic stem cells and characterized by the presence of primitive or atypical myeloid or lymphoid cells in the bone marrow and the blood. "In recent studies, ZFP36L2 was reported as a target of AML1 to induce the apoptosis of leukemia cells, suggesting its inhibitory role in tumor pathogenesis." (PMID 36627670, 2023). "Most of these are recurrent and class-defining in pAML (for example, KMT2Ar, 20.3%; RUNX1::RUNX1T1, 12.4%), whereas we also found fusions recurrent in other leukemias, such as SET::NUP214 (n = 1) or SFPQ::ZFP36L2 (n = 1)." (PMID 38212634, 2024). "While BMP-like leukemias harbored fusion products known to drive high HOXA cluster expression, including MLLT10, KMT2A, NUP214, and direct HOXA::TCR fusions, T-specified leukemias had fusions to ZFP36L2 (involved in cell cycle control during T-cell beta selection) and TLX1/3." (PMID 37961674, 2023).
gastric cancer (6 papers, 2019 to 2023). A primary or metastatic malignant neoplasm involving the stomach. "The authors showed that tandem duplication induced amplification of the super enhancers and were associated with an increase in ZFP36L2 expression in ~10% of gastric cancers." (PMID 32545247, 2020). "Here, the authors perform whole-genome sequencing on 168 gastric cancer patients and identified tandem-duplications of super-enhancer ZFP36L2 in 10% of gastric cancer, and mutational signatures in tumors with cadherin 1 mutations that associated with poor prognoses." (PMID 31048690, 2019). "However, the findings were inconsistent with previously reported data that revealed the expression of ZFP36L2 to be increased in 10% of gastric cancer, and ZFP36L2 to promote tumor proliferation." (PMID 35343095, 2022). "Conversely, ZFP36L2 has been reported to have oncogenic activity in gastric cancer and pancreatic cancer, suggesting that ZFP36L2 may adopt cell type-specific functions of which the biological relevance should be further investigated." (PMID 35008519, 2021). "Functionally, ZFP36L2 promoted the growth of gastric cancer cells in this study." (PMID 32545247, 2020). "The overexpression of ZFP36L2 promotes growth and malignancy of gastric cancer (GC) cells, and its transcription levels are regulated by a tandem duplication in the SE region." (PMID 36923930, 2023).
pancreatic ductal adenocarcinoma (6 papers, 2019 to 2024). An infiltrating adenocarcinoma that arises from the epithelial cells of the pancreas. "In the case of pancreatic ductal adenocarcinoma, high expression of ZFP36L2 predicts shorter survival, and silencing it inhibits cancer cell aggressiveness." (PMID 35366242, 2022). "ZFP36L2 is an RNA-binding protein regulating cell cycle that contributes to pathogenesis of pancreatic ductal adenocarcinoma (PDAC)." (PMID 33854844, 2021). "For example, in pancreatic ductal adenocarcinoma (Panc-AdenoCA; N = 232), the addition of functional adjustment to the algorithm resulted in a gain of three additional drivers (ACVR1B, RBM10 and ZFP36L2) and the loss of one likely false-positive genes (FAU)." (PMID 32024818, 2020). "Notably, ZFP36L2 is a tissue-specific protein that enhances the invasiveness of cancer cells, as observed in pancreatic ductal adenocarcinoma." (PMID 39767767, 2024). "ZFP36L2 was overexpressed in pancreatic ductal adenocarcinoma (PDAC) tissues and cells as a result of suppression of microRNA-375, indicating the involvement of ZFP36L2-regulated pathways in PDAC pathogenesis." (PMID 32545247, 2020).
acute lymphoblastic leukemia (5 papers, 2016 to 2021). Leukemia with an acute onset, characterized by the presence of lymphoblasts in the bone marrow and the peripheral blood. "Intriguingly, mice carrying double-deficiency of Zfp36l1 and Zfp36l2 in T-cell lineage results in the arrest of thymopoiesis at the double-negative stage and develop T cell acute lymphoblastic leukemia (T-ALL) due to aberrant activation of Notch signaling." (PMID 32655569, 2020). "Recently, the genomic landscape of large cohorts of T-lineage acute lymphoblastic leukemia (T-ALL) was revealed, and a spontaneous frame-shift mutation of ZFP36L2 (at residue 105) was identified as a putative driver for childhood T-ALL." (PMID 29449217, 2018). "Importantly, double-deficiency of ZFP36L1 and ZFP36L2 in T-cell lineage in mice causes the arrest of thymopoiesis at the double-negative stage and develops T cell acute lymphoblastic leukemia (T-ALL) due to aberrant activation of Notch signaling." (PMID 34276705, 2021). "Similarly, mice deficient for ZFP36L1 and ZFP36L2 displayed altered T cell development and readily succumbed to CD8+ T cell acute lymphoblastic leukemia." (PMID 27690235, 2016).
T-cell acute lymphoblastic leukemia (5 papers, 2018 to 2025). Acute lymphoblastic leukemia of T-cell origin. "Deletion of the genes Zfp36L1 and Zfp36L2, which encode RNA-binding proteins, was shown to cause T-cell acute lymphoblastic leukemia (T-ALL) in mice due to impaired Notch1 mRNA degradation." (PMID 30144809, 2018). "Experimental studies in animal models have shown that when the mouse T cell lineage carries ZFP36L2 deficiency, the thymogenesis process will be stalled, and T-cell acute lymphoblastic leukemia may develop." (PMID 35928229, 2022). "Previous work has shown that mice with double KO of Zfp36l1 and Zfp36l2 in T cells during thymopoiesis develop T cell acute lymphoblastic leukemia because of changes in Notch-1 signaling." (PMID 37903626, 2024). "Indeed, ZFP36L1 and ZFP36L2 suppressed NOTCH1 expression in T cell acute lymphoblastic leukemia by interacting with the 3′ UTR of NOTCH1." (PMID 37853162, 2023). "However, mice with single KO of Zfp36l1 or Zfp36l2 individually in T cells during thymic development do not develop T cell acute lymphoblastic leukemia, suggesting that Zfp36l1 and Zfp36l2 may have redundant functions in T cells." (PMID 37903626, 2024).
breast carcinoma (4 papers, 2013 to 2024). "However, in breast cancer, lung cancer, melanoma and cervical cancer, the expression of ZFP36L2 was low." (PMID 35910229, 2022).
colon cancer (4 papers, 2021 to 2023). "ZFP36, ZFP36L1 and ZFP36L2 mRNA levels were generally increased in the colon cancer cells by high concentration of LPS treatment." (PMID 37705049, 2023). "qPCR showed that TTP and ZFP36L1 genes were expressed in similar levels but ZFP36L2 mRNA was barely detectable in the colon cancer cells." (PMID 37705049, 2023). "SYBR Green qPCR showed that TTP/ZFP36 and ZFP36L1 were expressed in similar levels but ZFP36L2 mRNA was barely detectable in the colon cancer cells." (PMID 33723275, 2021). "TTP family mRNA levels (ZFP36, ZFP36L1 and ZFP36L2 mRNAs) were generally decreased and TTP-targeted cytokine mRNA levels (TNF, COX2, PPARR and RAB24 mRNAs) were relatively high in the colon cancer cells." (PMID 33723275, 2021).
pancreatic cancer (4 papers, 2021 to 2023). "ZFP36L2 is a previously validated miR-375 target in pancreatic carcinoma and known to code for an RNA binding protein that can destabilize RNA transcripts containing AU-rich elements." (PMID 37884859, 2023). "Furthermore, LRRC9-ART has been characterized at the expression level, and is predicted to interact with ZFP36L2, an RNA-binding protein that controls the cell cycle and is involved in pancreatic cancer." (PMID 34639169, 2021).
acute myeloid leukemia (3 papers, 2020 to 2024). Acute myeloid leukemia (AML) is a group of neoplasms arising from precursor cells committed to the myeloid cell-line differentiation. "We select six representative genes from CancerMine, which include three most frequently reported genes in the context of acute myeloid leukemia (AML), KMT2A, FLT3, and MLLT3, as well as three genes that are least reported in this specific cancer, namely ZFP36L2, ZIC2, and ZNF582." (PMID 38431735, 2024).
female infertility (3 papers, 2007 to 2022). Diminished or absent ability of a female to achieve conception. "We chose the ovary because it is the organ with the second highest Zfp36l2 expression and this gene has been implicated in mouse female infertility." (PMID 35380695, 2022). "Two models revealed a female infertility phenotype; however, biologically significant effects of Zfp36l2 knockdown were observed in other tissues, including red blood cell differentiation." (PMID 35380695, 2022). "Recently, the female infertility phenotype was confirmed using an elegant mouse model in which Zfp36l2 was specifically removed from the oocytes." (PMID 35380695, 2022). "This suggests that the physiological role of ZFP36L2 is likely broader than just its role in female infertility." (PMID 35380695, 2022). "Using knowledge obtained by studying a genetically engineered mouse model, we propose a new molecular basis for unexplained female infertility involving the ZFP36L2 RNA-binding protein's role in ovulation and oocyte maturation." (PMID 24830504, 2014). "Our results suggest that decreased ZFP36L2 expression can, conceivably, be the basis of some cases of unexplained female infertility in humans." (PMID 24830504, 2014). "Our data support an important role for this new specific RNA/protein interaction in the physiopathology of female infertility, pointing to ZFP36L2, as a critical factor in post-transcriptional regulation of LHR mRNA." (PMID 24830504, 2014). "Mice with decreased levels of an amino-terminal truncated form of ZFP36L2 exhibit female infertility and disrupted early embryonic development." (PMID 17207279, 2007).
Infertility (3 papers, 2014 to 2019). "Possibly, mutations or genetic polymorphisms of ZFP36L2 might be found in women with infertility presenting with anovulation and/or oocyte immaturity in IVF cycles." (PMID 24830504, 2014). "It was reported that mice that lack the N-terminal 29 amino acids of ZFP36L2 are infertile, due to failure to control expression of luteinizing hormone receptor (LHR) by ZFP36L2." (PMID 31118942, 2019).
Arthritis (2 papers, 2021 to 2024). Inflammation of a joint. "We found that simultaneous deficiency of Zfp36, Zfp36l1, and Zfp36l2 in myeloid cells led to the spontaneous development of an early lethal phenotype, with severe arthritis, myeloid hyperplasia, bone resorption, and increased levels of cytokines and chemokines." (PMID 37903626, 2024). "The failure of weight gain, arthritis, and early death could be prevented completely by two normal alleles of any of the three paralogues, and even one normal allele of Zfp36 or Zfp36l2 was enough to prevent the inflammatory phenotype." (PMID 37903626, 2024).